NUMB (NUMB endocytic adaptor protein)
Diseases named in the same sentence as NUMB in open-access papers (continued):
Sharing a sentence is not in itself a finding about the gene and the disease.
adenomyosis (1 paper, 2025). The growth of endometrial tissue inside the muscular wall of the uterine corpus. "The observed 3.2-fold increase in NUMB expression in adenomyotic tissues compared to controls (p < 0.001) establishes NUMB as a potential diagnostic biomarker for adenomyosis." (PMID 41614791, 2025). "The significant increase in myometrial NUMB expression showed positive correlations with clinical parameters including dysmenorrhea severity suggesting that NUMB upregulation may be associated with symptom severity and disease extent in adenomyosis patients." (PMID 41614791, 2025). "Our finding that NUMB alterations are associated with improved survival (92% vs. 73% at 100 months) aligns with this literature and suggests that NUMB may be a key molecular mediator of the protective effects observed in adenomyosis-associated endometrial pathology." (PMID 41614791, 2025). "First, the observed elevated expression levels of NUMB in adenomyosis tissues (2–3-fold higher than controls) establishes NUMB as a potential diagnostic biomarker for adenomyosis." (PMID 41614791, 2025). "In our pilot study, we found that NUMB protein is significantly upregulated in the myometrium of adenomyosis patients." (PMID 41614791, 2025). "This analysis provides insights into NUMB alterations across the spectrum of endometrial diseases, from benign conditions like adenomyosis to malignant transformation." (PMID 41614791, 2025). "This analysis provides crucial insights into the prognostic value of NUMB dysregulation and its potential clinical implications for adenomyosis management." (PMID 41614791, 2025). "For the first time, we have shown the expression of NUMB in adenomyosis tissues from 21 patients compared to 14 controls." (PMID 41614791, 2025). "This study presents the first evidence of altered NUMB expression in adenomyosis, demonstrating significant upregulation in both eutopic endometrium and myometrium compared to controls." (PMID 41614791, 2025). "Future studies should focus on functional validation of NUMB’s role in adenomyosis pathogenesis through in vitro and in vivo models." (PMID 41614791, 2025). "Regarding the potential of NUMB as a therapeutic target specific to adenomyosis, several considerations support this possibility despite its presence in normal endometrium and myometrium." (PMID 41614791, 2025). "The clinical significance of elevated NUMB expression in adenomyosis represents a paradigm shift in understanding endometrial stem cell dysregulation in this condition." (PMID 41614791, 2025). "Our study provides the first molecular characterization of NUMB in adenomyosis, filling a critical gap in understanding stem cell regulatory mechanisms in this condition." (PMID 41614791, 2025). "An important consideration in interpreting our findings is the apparent contradiction with a previous study published in 2015, which reported significantly reduced NUMB expression in uterine adenomyosis." (PMID 41614791, 2025). "This supports the hypothesis that NUMB dysregulation in adenomyosis may represent an adaptive response that, while contributing to adenomyosis pathogenesis, may also confer protective effects against more aggressive malignant transformation." (PMID 41614791, 2025). "Our study demonstrates altered NUMB expression patterns in human adenomyosis tissues, which may indicate its potential utility as a stem cell marker associated with this disorder." (PMID 41614791, 2025). "Notably, we observed differential expression of NUMB in the eutopic endometrium of adenomyosis patients compared to healthy controls, indicating a possible dysregulation of stem cell-related pathways in adenomyosis." (PMID 41614791, 2025). "This pattern suggests that NUMB dysregulation affects individual cell fate decisions rather than representing clonal expansion, supporting the stem cell dysregulation hypothesis in adenomyosis pathogenesis." (PMID 41614791, 2025).
adenomyosis (continued). "The correlation between NUMB expression levels and clinical symptom severity provides an objective measure of disease activity, which is particularly valuable given the current limitations in adenomyosis diagnosis that rely heavily on imaging modalities with variable sensitivity and specificity." (PMID 41614791, 2025). "Moreover, cancers arising in the context of adenomyosis may have different molecular characteristics, potentially including altered NUMB expression patterns that confer less aggressive behavior." (PMID 41614791, 2025).
breast tumor (1 paper, 2016). "Together, these findings reveal novel functions of NUMB in the regulation of breast tumor EMT, especially in the TNBC subtype." (PMID 27506933, 2016). "Collectively, these findings reveal novel molecular mechanisms of NUMB in the regulation of breast tumor EMT, especially in TNBC." (PMID 27506933, 2016). "We expanded our observations using immunohistochemistry staining of NUMB in 150 human breast tumor samples." (PMID 27506933, 2016).
cervical intraepithelial neoplasia (1 paper, 2018). "We aimed to investigate the role of NOTCH1 and NUMB expression and their localization in cervical intraepithelial neoplasia (CIN) and ICC samples." (PMID 29721172, 2018).
cholangiocarcinoma (1 paper, 2023). A carcinoma that arises from the intrahepatic biliary tree (intrahepatic cholangiocarcinoma) or from the junction, or adjacent to the junction, of the right and left hepatic ducts (hilar cholangiocarcinoma). "In contrast, the expression of NUMB was observably elevated in cholangiocarcinoma (CHOL), esophageal carcinoma (ESCA), head and neck squamous cell carcinoma (HNSC), liver hepatocellular carcinoma (LIHC), and stomach adenocarcinoma (STAD), compared to normal controls." (PMID 37657045, 2023).
colorectal tumor (1 paper, 2024). "Zhang analyzed the role of Numb in tumor by searching literature with various software, suggesting that in colorectal cancer, NUMBL inhibits Notch pathway in colorectal tumor with unchanged NUMB expression, and the decrease in NUMBL expression leads to increased malignancies and poor prognosis." (PMID 39691600, 2024).
congenital heart disease (1 paper, 2022). A heart disease that is present at birth. "NUMB plays an important role in cardiac progenitor cell differentiation and cardiac morphogenesis and serves as a potential candidate gene for cardiac regeneration and treatment of congenital heart disease." (PMID 35114641, 2022).
diabetes (1 paper, 2023). "The results revealed that IRAK1, TRAF6, NUMB, and STX3 are direct targets of miR-146 in the context of diabetes." (PMID 37560309, 2023). "The analysis of individual studies on miR-146 in the context of diabetes yielded a heatmap that showcased the prevalence of several genes, namely IRAK1, TRAF6, IL-6, TNF-α, NUMB, EGFR, and TGFβ-1, among others." (PMID 37560309, 2023).
diffuse large B-cell lymphoma (1 paper, 2023). "In lymphoid neoplasm diffuse large B-cell lymphoma (DLBC), ovarian serous cystadenocarcinoma (OV), thymoma (THYM), and uterine carcinosarcoma (UCS), the expression of NUMB was lower than counterpart controls." (PMID 37657045, 2023).
endometrial adenocarcinoma (1 paper, 2025). "Melatonin has been found to inhibit 17β-estradiol (E2)-induced proliferation, invasion, and EMT in endometrial adenocarcinoma cells by upregulating NUMB and E-cadherin, indicating a potential role for NUMB-targeting hormonal therapies." (PMID 40296944, 2025).
gallbladder cancer (1 paper, 2023). "In order to further elucidate the effect of the ZFP64–HDAC1 axis on the NUMB–Notch1 signaling pathway, HDAC1 was overexpressed in gallbladder cancer cell lines with ZFP64 knockdown." (PMID 37760477, 2023).
gastric cancer (1 paper, 2016). A primary or metastatic malignant neoplasm involving the stomach. "We will further investigate the role of NUMB in peritoneal metastatic gastric cancer in a future study." (PMID 27270314, 2016).
gout (1 paper, 2024). A condition characterized by painful swelling of the joints, which is caused by deposition of urate crystals. "Our present work uncovers an imperceptible mechanism underlying the causative link between NUMB and hyperuricemia/gout." (PMID 39433541, 2024). "In summary, we have uncovered a novel NUMB-mediated mechanism of uric acid excretion and a functional missense variant of NUMB in humans, which causes hyperuricemia and gout." (PMID 39433541, 2024). "Here, we report a rare genetic variant of gout-unprecedented NUMB gene within a hereditary human gout family, which was identified by an unbiased genome-wide sequencing approach." (PMID 39433541, 2024). "Whole-exome sequencing analysis of 5 gout and hyperuricemia individuals identified a missense variant of NUMB commonly present in all gout-affected family members tested." (PMID 39433541, 2024). "Owing to the heterozygosity of the genetic aberration, the decreased levels of the WT NUMB is sufficient to cause hyperuricemia and gout." (PMID 39433541, 2024). "This NUMB function encouraged us to investigate its variant role on causing hyperuricemia and gout." (PMID 39433541, 2024). "To define NUMB rs374597310 and BHMT rs752243322 for causing hyperuricemia and gout, we investigated the functions of these two genes." (PMID 39433541, 2024). "Along this view, any factors, including genetic or attained factors that alter the optimal ratio between NUMB and ABCG2 would potentially cause hyperuricemia and gout." (PMID 39433541, 2024). "On the basis of these findings, we propose that normalization of NUMB function provides an important therapeutic approach for treating hyperuricemia and gout." (PMID 39433541, 2024). "Together, our findings provide novel mechanistic insights into the complex interaction of NUMB with a membrane transporter in polarized cells in determining gout development." (PMID 39433541, 2024). "Therefore, normalization of NUMB function provides an exciting and attractive approach for treating hyperuricemia/gout and possible other human diseases." (PMID 39433541, 2024).
liver cancer (1 paper, 2023). An epithelial or non-epithelial malignant neoplasm that arises from the liver. "To that end, we examined the relative expression levels of NUMB-PTBS and NUMB-PTBL in multiple liver cancer cell lines." (PMID 37843276, 2023). "Interestingly, NUMB isoforms 3 and 4, which have a truncated phosphotyrosine-binding (PTB) domain and are thus unable to interact with phosphorylated SPTAN1 and activate MST1/2, were selectively upregulated in liver cancer, which correlated with YAP activation." (PMID 37843276, 2023).
lung fibrosis (1 paper, 2021). "Since the activation of Wnt-β-catenin signaling in lung epithelial cells plays a critical role in promoting lung fibrosis, we analyzed whether NUMB influences the expression and activation of β-catenin." (PMID 34124033, 2021).
lymphoma (1 paper, 2023). A malignant (clonal) proliferation of B- lymphocytes or T- lymphocytes which involves the lymph nodes, bone marrow and/or extranodal sites. "We demonstrate that there is decreased NUMB and increased MDM2 expression in NOTCH1 overexpressing lymphomas." (PMID 37160922, 2023).
metastatic melanoma (1 paper, 2022). A melanoma that has spread from its primary site to another anatomic site. "NUMB protein expression was downregulated in three of four metastatic melanoma cell lines in the nucleus." (PMID 34883044, 2022). "Moreover, NUMB expression is downregulated in metastatic melanoma cells." (PMID 34883044, 2022).
myeloid leukemia (1 paper, 2014). A clonal proliferation of myeloid cells and their precursors in the bone marrow, peripheral blood, and spleen. "Loss of MSI2 restores NUMB expression and impairs the blast crisis phase of myeloid leukemia." (PMID 24935936, 2014). "The crisis phase of myeloid leukemia is marked by low NUMB expression." (PMID 24935936, 2014).
myeloid malignancies (1 paper, 2021). "In myeloid malignancies, HOXA9 upregulates MSI2, and MSI2 then downregulates NUMB, a negative regulator of NOTCH, thereby promoting cell division during blast crisis." (PMID 33504942, 2021).
psoriasis (1 paper, 2022). An autoimmune condition characterized by red, well-delineated plaques with silvery scales that are usually on the extensor surfaces and scalp. "miR-146b facilitated miRNA-146a to inhibit the proliferation and psoriasis-related target gene expression (such as FERM domain containing kindlin 1 (FERMT1), NUMB endocytic adaptor protein (NUMB), etc.)in cultured human keratinocytes stimulated with IFN-γ or TNF-α." (PMID 35075118, 2022).
renal carcinoma (1 paper, 2017). A carcinoma arising from the epithelium of the renal parenchyma or the renal pelvis. "Out of the unique set of genes detected by BNNPT, a few were reported to be relevant to renal cancer or disease: CDCP1, GSTT1, E2F3, MAPK1, SALL4, SIRT1, ADAMTS13, Gfrα1, ASPH, MIR17HG, APOE, BMP4, RCOR1, NUMB and SEC63." (PMID 28986523, 2017).
schizophrenia (1 paper, 2020). A major psychotic disorder characterized by abnormalities in the perception or expression of reality. "Cluster IV with keywords metabolism, mRNA, ribosome, viral protein, NUMB, etc. is significantly altered only in schizophrenia DLPFC layers, which indicates protein synthesis dysfunction." (PMID 32599927, 2020).
uterine corpus endometrial carcinoma (1 paper, 2023). A endometrial carcinoma (disease) that involves the body of uterus. "Besides, genetic alternations of NUMB and NUMBL focused on uterine corpus endometrial carcinoma, and higher genetic mutations of NUMBL were correlated with more prolonged overall survival and disease-free survival in different cancers." (PMID 37657045, 2023).
viral infection (1 paper, 2023). "Moreover, in mice either expressing an active form of Notch1 in Tregs (Foxp3EGFPCreR26N1c/+) or lacking NUMB expression in these cells (Foxp3EGFPCreNumbΔ/Δ), treatment with polyinosinic:polycytidylic acid (poly I:C) to simulate viral infection induced systemic inflammation." (PMID 36282598, 2023).
tumor (73 papers, 2013 to 2026). "Misregulated expression of NUMB is linked to a number of disease states including cancer where it acts as both a tumor suppressor and a tumor promotor." (PMID 39863103, 2025). "The association between NUMB expression and recurrence is consistent with the observation that NUMB 3 patients also exhibited higher tumor grade, as confirmed by both chi-squared analysis and Spearman correlation." (PMID 40296944, 2025). "The sum of our results argues that the hyper‐degradation of NUMB by the CRL7FBXW8 complex is causal in the natural history of the tumor and represents a therapeutic vulnerability, paving the way for the development of novel targeted therapies for BC." (PMID 40411418, 2025). "Mis-regulation of NUMB alternative splicing is broadly associated with many cancer types and impacts several cellular processes associated with tumor progression." (PMID 39863103, 2025). "The loss or mutation of NUMB is associated with poor prognosis, tumor progression, and resistance to chemotherapy in NSCLC patients." (PMID 38791918, 2024). "MAP17 upregulation activated Notch pathway through segregating NUMB, which caused direct alteration of tumor sphere formation and Notch and Stem pathway transcription." (PMID 37403034, 2023). "It is encoded upstream of the NUMB protein gene, which can reduce tumor formation and prevent invasion in UM cell lines." (PMID 34439196, 2021). "Recent studies have revealed prevalent deletion of NUMB in various cancers, and loss of NUMB has been implicated in promoting tumor growth, invasion, metastasis, and stemness." (PMID 34045601, 2021). "NUMB is a tumor suppressor and cell fate determinant, and loss of NUMB expression has been observed in cancer." (PMID 33117795, 2020). "The increased inclusion exon 9 (ENSE00001689532) of NUMB transcripts is a highly widespread tumor-associated AS event, which was detected by exon arrays and validated by PCR in both of two independent laboratories." (PMID 24622401, 2014). "Thus, enhanced CRL7FBXW8 activity, through its interference with the tumor suppressor activity of NUMB, is a causal alteration in BC, suggesting it as a potential therapeutic target for precision medicine." (PMID 40411418, 2025). "In keeping with these findings, more recently, it has been documented that chemotherapy activates the EZH2/STAT3 pathway in tumor cells, causing an increase in miR-378a-3p and miR-378d levels, in both cells and exosomes, which finally target the Notch pathway suppressor NUMB." (PMID 35582386, 2021). "NUMB has been linked to human cancers as a tumor suppressor." (PMID 27506933, 2016). "The combined knockdown of TRAF6 and NUMB showed that NUMB does not seem to act in an additive or counteractive manner with TRAF6 during tumor suppression; it would suggest that TRAF6 and NUMB are likely to mediate independent cascades causing tumor suppression." (PMID 24302991, 2013). "Thus, knockdown of MSI2 causes both a large reduction in the growth of DAOY MB tumor cells and increases the expression of NUMB." (PMID 23667531, 2013). "Thus changes in isoform expression may provide an explanation for the tumor associated reduction of total NUMB protein levels through an unknown mechanism." (PMID 39863103, 2025).